MGAT5 (alpha-1,6-mannosylglycoprotein 6-beta-N-acetylglucosaminyltransferase)
Diseases named in the same sentence as MGAT5 in open-access papers (continued):
Sharing a sentence is not in itself a finding about the gene and the disease.
psoriasis (1 paper, 2019). An autoimmune condition characterized by red, well-delineated plaques with silvery scales that are usually on the extensor surfaces and scalp. "Meanwhile, MGAT5 gene was recently shown to be associated with psoriasis susceptibility in Spanish and European populations." (PMID 31130981, 2019).
steatosis (1 paper, 2023). Increased lipid within the cytoplasm of cells. "Indeed, Mgat5−/− mice on a normal diet age prematurely show steatosis and muscle weakness." (PMID 37918808, 2023).
type 1 diabetes (1 paper, 2023). "The glycosyltransferase loci MGAT5 (encoding alpha-1,6-mannosylglycoprotein 6-beta-N-acetylglucosaminyltransferase) and MGAT1 have been implicated in the pathogenesis of type 1 diabetes through N-glycan branching and its impact on T cell activation." (PMID 36907892, 2023).
tumor (76 papers, 2007 to 2026). "In fact, the deficiency of branched N-glycosylation, modeled in Mgat5 KO mice, was associated with a delay in cancer development and a lower number of tumor lesions." (PMID 40087977, 2025). "To functionally examine the role of immune pressure on the growth of Mgat5-deficient tumors, we subcutaneously implanted EV or Mgat5-KO tumor cells from a T cell–inflamed clone (2838c3) into NOD/SCID mice lacking functional T cells, B cells, and NK cells." (PMID 38912584, 2024). "In contrast with the protective effects conferred by live Mgat5-KO cells, mice immunized with dead EV or Mgat5-KO cells were susceptible to tumor rechallenge, with Mgat5-WT cells able to grow at the same rate as they did in a naive host." (PMID 38912584, 2024). "Tumor implantation into Batf3–/– mice rescued the Mgat5-KO growth deficiency that was most pronounced at early time points." (PMID 38912584, 2024). "Whereas Mgat5-deficient cells exhibited normal growth in vitro and in immunodeficient hosts in vivo, tumor formation was almost completely abolished in immunocompetent hosts in vivo." (PMID 38912584, 2024). "Loss of Mgat5 results in tumor clearance that is dependent on T cells and dendritic cells, with NK cells playing an early role." (PMID 38912584, 2024). "To determine the effects of Mgat5 loss on tumor clearance in an immunosuppressive microenvironment, we used CRISPR to KO Mgat5 in 2 non–T cell–inflamed (“cold”) clonal cell lines (6694c2 and 6419c5), which reflect the myeloid-rich TME of most PDAC tumors." (PMID 38912584, 2024). "It is believed that in tumor cells, Ras oncogene mutation leads to overexpression of MGAT-5, the glycosyltransferase responsible for adding a β-1,6-N-acetylglucosamine to the core of N-glycans." (PMID 33923867, 2021). "The MGAT5 expression also caused an increased diameter of tumor spheres, which was more pronounced in the soft-agar beds." (PMID 28178684, 2017). "In addition, Mgat5 KO mice exhibited, at the latest timepoint, a significantly lower number of tumor lesions with smaller sizes than WT mice, which support that a deficiency in Mgat5-mediated branched N-glycans delays CAC progression." (PMID 40087977, 2025). "Expression of N-acetylglucosaminyltransferase V (encoded by Mgat5 or GnT-V), which catalyzes the addition of β1,6-linked N-acetylglucosamine to form complex N-glycans, has been linked to tumor growth and metastasis across tumor types." (PMID 38912584, 2024). "Notably, these same Vβ receptor subtypes were enriched in both CD4+ and CD8+ T cells, suggesting a polyclonal T cell response to tumor-associated antigens in Mgat5-WT tumors." (PMID 38912584, 2024). "Moreover, Mgat5 protected HCC tumor cells from anoikis, a form of cell death following loss of cell-matrix interactions." (PMID 38912584, 2024). "Mgat5 deficiency confers a tumor cell–autonomous sensitivity to immune pressure." (PMID 38912584, 2024). "Likewise, Mgat5-deficient Hep55 cells exhibited spontaneous tumor regressions in vivo, following the pattern of initial growth followed by rapid rejection, as seen in the PDAC lines." (PMID 38912584, 2024). "Loss of Mgat5 increases the immunogenicity of existing tumor antigens." (PMID 38912584, 2024). "Thus, loss of Mgat5 results in a profound inability of PDAC tumor cells to grow in vivo in the setting of both T cell–inflamed and non–T cell–inflamed tumors." (PMID 38912584, 2024). "The alternation of tumor cell glycosylation is usually caused by the change of the expression of glycosyltransferase in the Golgi apparatus of tumor cells, the most common of which is the number and branch of N-linked glycans mediated by MGAT5." (PMID 37427332, 2023). "MGAT5 expression is in many cases associated with tumor progression and metastatic potential." (PMID 32849657, 2020). "GnT5 deficiency (Mgat5-deficient mice) resulted in reduced tumor growth and metastasis." (PMID 24592356, 2014).
tumor (continued). "Next, we examined mice bearing Mgat5-KO tumors to determine whether there was an expansion of T cells expressing Vβ alleles that differed from naive and WT tumor–bearing mice, which might reflect a T cell response to antigens present exclusively in Mgat5-KO cells." (PMID 38912584, 2024). "Allogeneic killing triggered by L-PHA was reduced by lowering β1,6-branching both in tumor cells via MGAT5 deletion (clone B2) or in T cells via MGAT1 deletion." (PMID 41005308, 2025). "Increased MGAT5 expression in cancer promotes EMT and tumor invasiveness and is strongly associated with a poor prognosis." (PMID 41408046, 2025). "Second, any Mgat5-KO–related neoantigens strong enough to result in T cell–mediated tumor clearance would be expected to reshape the T cell receptor repertoire." (PMID 38912584, 2024). "Less well understood is the role of Mgat5 glycans in modulating tumor cell responses to pro-death stimuli." (PMID 38912584, 2024). "We injected C57BL/6 mice with either 6694c2 EV or Mgat5-KO cells and treated tumor-bearing animals with a combination of PD-1– and CTLA4-blocking antibodies when tumors reached 50–100 mm3 in volume." (PMID 38912584, 2024). "To test this possibility, we cultured T cell–inflamed Mgat5-KO or EV tumor cells with increasing concentrations of TNF-α, TRAIL, or FasL, and measured cell death." (PMID 38912584, 2024). "To this end, we subcutaneously implanted Mgat5-KO and control wild-type (WT) tumor cells into Batf3–/– hosts, which lack conventional type 1 DCs (cDC1s) that are specialized for CD8+ T cell activation and cross-presentation." (PMID 38912584, 2024). "Mgat5 expression has prognostic significance in HCC, and Mgat5 influences multiple aspects of tumor biology." (PMID 38912584, 2024). "Despite this handicap, the addition of ICB treatment led to a significant decrease in tumor growth and improved survival of mice bearing Mgat5-KO tumors." (PMID 38912584, 2024). "Immunofluorescence (IF) for PHA-L confirmed Mgat5 KO in vivo, while further staining revealed significant increases in tumor-infiltrating CD8+ T cells." (PMID 38912584, 2024). "Rather, our findings suggest that Mgat5 glycans impede the activity and function of tumor-specific T cells and that their elimination enhances immunogenicity in an antigen-agnostic manner." (PMID 38912584, 2024). "To further explore the role of T cells in the rejection of Mgat5-deficient tumors, we depleted CD4+ and CD8+ T cells separately and found that each depletion led to a partial rescue of Mgat5-KO tumor growth." (PMID 38912584, 2024). "Dysregulation of Mgat5 has previously been reported to promote cancer progression in various tumor types, and studies in PDAC have suggested that Mgat5 glycans interfere with the formation of the immunological synapse between T cells and cancer cells." (PMID 38912584, 2024). "To this end, we isolated splenocytes from naive C57BL/6 mice or mice injected with Mgat5-WT or Mgat5-KO tumor cells for T cell receptor Vβ repertoire analysis of both CD4+ and CD8+ T cells." (PMID 38912584, 2024). "RUNX2 knockdown also led to the decreased levels of RUNX2, MMP13 and MGAT5 in mice tumor tissues when assessed by western blotting or IHC assay." (PMID 37256183, 2023). "MGAT5 has been shown to remodel the tumor microenvironment and accelerate tumor cell growth and metastasis through promoting the collapse of the extracellular matrix and enhancing the release of glycosyltransferase binding cytokines, including VEGF and MMPs." (PMID 37256183, 2023). "Knockdown of MGAT5 and up-regulation of Pcdhβ inhibits the growth of tumor cells, reduces the proportion of impregnated tumor cells, and reduces the formation of solid tumors." (PMID 37427332, 2023). "MGAT5 regulates mesenchymal markers, growth factor receptors, and even immune cell infiltration to influence the malignant transformation and tumor metastasis of cells." (PMID 36185271, 2022).
tumor (continued). "Consistent with our findings, several studies have reported that elevated MGAT5 expression can increase branched complex N-glycan attachment to cadherins and integrins, which in turn modulate tumor adhesion." (PMID 34752419, 2021). "Inhibition of MGAT5 reduces tumor growth, enhances the anti-tumor responses by CD4+ T cells and macrophages, and promotes Th1 differentiation." (PMID 32849657, 2020). "In fact, Mgat5 knockout mice, the enzyme responsible for the addition of complex N-glycan branches, exhibit delayed tumor growth and a general decrease of growth factor signaling." (PMID 29515119, 2018). "MGAT5 expression has been shown to harness cancer metastasis in a mouse model in vivo, and the overexpression of the MGAT5 gene has been found in various tumor cells and tissues." (PMID 28178684, 2017). "In human colon carcinoma WiDr cells, very interesting results showed that the aberrant glycosylation of TIMP-1 (tissue inhibitor of metalloproteinase-1), through MGAT5 overexpression, increases the malignant behavior and promotes the tumor growth rate." (PMID 26539643, 2016). "On the one hand, increased E-cadherin modification with β1,6-branched N-glycans, which is catalyzed by MGAT5, is able to induce a destabilization of E-cadherin-mediated cell-cell adhesion with consequences to tumor progression." (PMID 26539643, 2016). "Tumor cells from Mgat5-/- mice fail to undergo epithelial-to-mesenchymal transition and are insensitive to multiple cytokines, including epidermal growth factor (EGF), patelet-derived growth factor (PDGF) and transforming growth factor beta (TGF-ß)." (PMID 26760037, 2016). "On the other hand, Mgat5 knockout (KO) mice have been shown to present suppressed polyomavirus middle T antigen-induced tumor growth and metastasis." (PMID 24982845, 2014). "Despite the low number of papers published on the direct effects of Mgat5 activity on galectin-3 function, both proteins are increased during tumor progression and deserve attention as suitable targets in malignant diseases." (PMID 24982845, 2014). "Moreover, exogenously added galectin-3 interacts with Mgat5-modified N-linked oligosaccharides on the surface of mammary carcinoma cells and stimulates α5β1-integrin activation, enhancing fibronectin fibrillogenesis and fibronectin-dependent tumor cell spreading, and motility." (PMID 24982845, 2014). "Knockdown of Mgat5 in mice, as well as Mgat1 knockdown in cells, results in a decrease in tumor incidence, growth and metastasis." (PMID 24040379, 2013). "Simultaneous single-particle imaging and super-resolution movie observation revealed that knocking out the glycosyltransferase MGAT5, which synthesizes highly branched complex-type N-glycans, reduced the binding ability of tumor-derived sEVs to laminin on both glass and recipient cell membranes." (PMID 42134545, 2026). "MGAT5 encoding a glycosyltransferase was found overexpressed in a variety of malignancies, unlike our findings, whose loss function was noted for tumor suppression and inhibition of metastasis, implicating different roles for PGCA pathogenesis." (PMID 40873563, 2025). "First, immunological memory (resulting in the rejection of tumor cells upon rechallenge) depends on a live T cell–tumor cell interaction, suggesting that new antigens formed as a consequence of the Mgat5 KO (if any) are insufficiently strong on their own to generate a durable immune response." (PMID 38912584, 2024). "CD4+/CD8+ T cell depletion led to full rescue of Mgat5-KO tumor growth." (PMID 38912584, 2024). "Notably, the same receptor subtypes (Vβ2, Vβ7, and Vβ8.1) that were expanded upon clearance of Mgat5-KO tumors were also found to be expanded on day 3 after challenge with Mgat5-WT tumor cells, along with Vβ3 and Vβ5." (PMID 38912584, 2024). "Subcutaneous injection in vivo, however, revealed no tumor growth deficiencies in the Mgat5-KO line." (PMID 38912584, 2024).
tumor (continued). "To test this hypothesis, we performed tumor immunization studies to determine whether live cell interactions are required for the immune response to Mgat5-KO cells." (PMID 38912584, 2024). "In addition, the apoptotic marker cleaved caspase-3 (CC3) was significantly increased in Mgat5-KO tumor cells, indicating increased cancer cell death." (PMID 38912584, 2024). "Finally, Mgat5 knockout in an immunotherapy-resistant PDAC line significantly decreased tumor growth and increased survival upon immune checkpoint blockade." (PMID 38912584, 2024). "Given that our standard injection approach resulted in Mgat5-KO tumors that were too small for immune profiling (even at the point of maximal size; 12 days), 10-fold more tumor cells (2 × 106) were injected into C57BL/6 mice to obtain tumors that would be adequate for flow cytometry." (PMID 38912584, 2024). "Both the 1 mg/kg and 4 mg/kg swainsonine dosages prompted a significant decrease in tumor growth compared with vehicle control–treated tumors, indicating that pharmacologic inhibition of N-glycosylation can phenocopy disruption of the Mgat5 gene." (PMID 38912584, 2024). "MGAT5 is an important N-glycan processing enzyme distributed in the Golgi apparatus, which can change the glycan structure of cell surface glycoproteins and thus aggravate the malignant transformation of cells and tumor metastasis." (PMID 37427332, 2023). "Tumor growth and metastasis are strongly suppressed in Mgat5 knockout mice and cells." (PMID 33963380, 2021). "Also, the ablation of MGAT5 mRNA in tumor cells leads to less metastatic and less responsive to cytokines phenotype, and STT3B participates in the epithelial-mesenchymal transition (EMT) in cancer cells." (PMID 33425736, 2020). "MGAT5 is known to promote both cell growth, cell motility, leading to tumour progression." (PMID 32888398, 2020). "Feasible explanations of these differences could be that the expression level of Mgat5 is unrepresentative of the amount of β1,6-branched N-glycans, or perhaps tumor cell lines versus cancerous tissue." (PMID 29902282, 2018). "The upregulation of MGAT5 expression implies that tumor cells may be armored with altered glycan conformations and that MGAT5 has a critical role in the formation of such pro-metastatic glycan alterations." (PMID 28178684, 2017). "Additionally, tumor specimens examined via RT-PCR and compared with the corresponding mucosa from each patient showed that MGAT5 expression is significantly enhanced in colorectal adenomas, carcinomas, and liver metastases." (PMID 26539643, 2016). "Mgat5-related changes in protein/lipid glycosylation on cell surface lead to alterations in the clustering of membrane proteins through lattice formation, resulting in functional advantages for tumor cells." (PMID 24982845, 2014). "Increased β1-6 branching of other Mgat5 target proteins, such as cadherins, integrins, and other cytokine/growth factor receptors may enhance and promote tumor growth and metastasis." (PMID 24982845, 2014). "In addition to its glycosyltransferase function, MGAT5 is involved in tumor transformation." (PMID 36185271, 2022). "To examine the role of Mgat5 in PDAC tumor cell biology, we used CRISPR to inactivate Mgat5 in tumor cells from the T cell–inflamed clonal line 2838c3." (PMID 38912584, 2024). "Several glycosyltransferases, including MGAT5, FUT8, ST6GAL1, ST6GALNAC1 and ST8SIA1 have an established reputation as tumor-promoting enzymes." (PMID 35565254, 2022). "LGALS1, B4GALT6, and GALNT11 were upregulated and MGAT5, MAN1A1, MANBA, LUM, GALNT1 and 7, HAPLN3, and ST6GALNAC5 were downregulated in Fra-2 cl 1 select primary tumours, while MGAT4A was upregulated." (PMID 34693476, 2022). "In OSCC tumour tissues, an overexpression of MGAT5 (also known as GNT-V) enhanced CEACAM6 N-glycosylation, which in turn promoted EGFR signalling that correlated with poor prognosis." (PMID 36289103, 2022).
tumor (continued). "It has been revealed that miR-124-3p functions as a tumor suppressor in BC by targeting CBL and MGAT5." (PMID 36038549, 2022). "Enhanced expression of various glycosyltransferase enzymes, including N-acetylglucosaminyltransferase V (e.g., GalNAc-TV, GnT-V, MGAT5), are responsible for an increased number of N-glycans in tumor cells." (PMID 31167407, 2019). "Both over-expression of MGAT5 and MMP9 strongly correlates with poorer tumor differentiation, higher TNM stage, and poorer survival." (PMID 29069753, 2017). "To explore which immune populations mediate tumor rejection, we injected immunodepleting antibodies against either CD4+ and CD8+ T cells or NK cells into C57BL/6 mice bearing either T cell–inflamed EV or Mgat5-KO tumor cells (2838c3)." (PMID 38912584, 2024). "Mgat5 deletion in a non–T cell–inflamed (“cold”) PDAC tumor line synergized with ICB to significantly slow tumor growth, improve survival, and promote rare tumor regressions." (PMID 38912584, 2024). "However, most surviving tumor cells were PHA-L+, indicative of an immune response that cleared the Mgat5-KO cells and spared the Mgat5-WT cells." (PMID 38912584, 2024). "Hematoxylin & eosin (H&E) staining of T cell–inflamed EV and Mgat5-KO tumors harvested 12 days after injection (the time of maximal tumor size) revealed no obvious differences between KO and EV tumors." (PMID 38912584, 2024). "Although MGAT5 knockdown or 2DG treatment alone did not affect tumor size, they significantly sensitized HR-proficient tumors (KPCA and UPK10) to anti-PD-L1 treatment." (PMID 38565883, 2024). "Gains in some of the genes involved in invasive/migratory properties (MGAT5, PKP4, ITGB6), cell cycle progression and regulation of apoptosis (RBMS1), and angiogenesis (NRXN1) may be involved in tumor development and progression." (PMID 26432421, 2015). "The expression of all sialyltransferases and MGAT5 was significantly increased in the tumour bearing mice compared to mice without tumours (blank)." (PMID 24023608, 2013). "MGAT5, responsible for branching, was significantly increased in mice with tumours compared with those without, as well as in mice treated with pro-inflammatory COAM." (PMID 24023608, 2013). "Tumor growth and metastasis were suppressed in mice lacking Mgat5, an enzyme forming antenna-like oligosaccharides containing lactosamines." (PMID 21765917, 2011). "The role of Mgat5 in PDAC tumor biology has not been explored." (PMID 38912584, 2024).